TLR4 (toll like receptor 4)
Diseases named in the same sentence as TLR4 in open-access papers (continued):
Sharing a sentence is not in itself a finding about the gene and the disease.
tumor (continued). "Previously, we reported that the CRT fragment (recombinant sCRT/39-272) promoted tumor malignancy through TLR4- and S100A8/9-mediated MDSC differentiation and recruitment." (PMID 36249426, 2022). "For example, a study has shown that TLR4 expressed on dendritic cells plays an important role in promoting anti-tumour immune responses following chemotherapy." (PMID 35962138, 2022). "TLR4 expression appeared lower in tumour tissues than in peritumoral area and its expression at the cell membrane is tightly controlled and, in particular, TLR4 is internalised after the LPS binding." (PMID 35990515, 2022). "Stimulation of TLR4 by LPS promoted immunosuppressive cytokine production, resulting in tumor immune evasion in lung cancer cells." (PMID 35309296, 2022). "Another research revealed that M2-polarized macrophages promote EMT of HCC cells and accelerate tumor progression through the TLR4/STAT3 signaling pathway." (PMID 36451087, 2022). "We also demonstrated that PAUF’s tumor migration-promoting effects are exclusively through the TLR4/MyD88/NF-κB pathway." (PMID 36232715, 2022). "In pancreatic tumors, LPS stimulates tumor development and increases invasiveness in vivo through activation of NF-κB via TLR4 signaling." (PMID 35468924, 2022). "Although the autophagy of B cells remains poorly understood in tumor pathogenesis, B cell activation is induced by tumor-derived autophagosomes (Dribbles), which sequester various tumor antigens in a TLR4/MYD88-dependent manner." (PMID 35321516, 2022). "Mechanistically, these findings suggest that ferrichrome modulates macrophage iron metabolism in a TLR4-dependent manner, thus inducing the macrophage polarization state to be skewed toward a proinflammatory anti-tumor phenotype." (PMID 36333531, 2022). "Recent studies have suggested that TLR4 expression correlates with cancer progression and TLR4 plays a key role in disrupting tumor cell apoptosis regulation, decreasing tumor cell apoptosis, and promoting tumor cell proliferation." (PMID 36401285, 2022). "TLR4 is also expressed in different types of cells in the liver, including tumor, hepatic stellate, and kupffer cells." (PMID 35052775, 2022). "The anti-tumor immune signaling pathway is inhibited when receptor TLR4 is bound by the IL1B ligand in the microenvironment." (PMID 35164166, 2022). "Other studies have shown that activation of TLR4 can stimulate the release of highly immunosuppressive exosomes, promote tumor development, and help tumor cells evade immune surveillance." (PMID 36741380, 2022). "Engagement of the toll-Like Receptor 4 (TLR4) signal pathway contributes to the development of a favorable tumor microenvironment in solid tumors." (PMID 36303228, 2022). "Mechanistic experiments showed that gut microbiota activated Toll-like receptor 4 (TLR4), resulting in modulation of tumor-infiltrating immune cells toward a pro-inflammatory, TNF+ phenotype." (PMID 35474500, 2022). "Compared to paracancerous tissues (N), TLR4 (p-value < 0.01) was significantly down-regulated in tumor tissues (T)." (PMID 36230476, 2022). "With our results, the activation of TLR4 triggers NF-κB-mediated inflammatory response, while LIN28 and let-7 miRNA are indicated in tumor development and are associated with inflammation." (PMID 35955552, 2022). "TLR4 has a tumor-promoting effect; however, monophosphoryl lipid A, a TLR4 agonist, enhances the adaptive immune response by promoting Th1 cell differentiation and increasing IFN-γ expression levels." (PMID 35680568, 2022). "TLR4 is also expressed on tumor cells and holds a prominent role in inflammation-fueled cancer progression and metastasis." (PMID 35205801, 2022). "It has been suggested that the activation of the TLR4 present on the surface of tumor cells promotes tumor cell survival via the activation of nuclear factor-kappa B (NF-κB) signaling and antiapoptotic proteins." (PMID 35890276, 2022).
tumor (continued). "NETs enhance differentiation of regulatory T cells by promoting mitochondrial oxidative phosphorylation in naive CD4+ T cells via TLR4, amplifying tumor burden." (PMID 35574410, 2022). "In tumor studies, TLR4 has been reported to enhance the function of antigen-presenting cells (APCs), increase the production of pro-inflammatory cytokines as well as IFNs, and boost cytotoxic responses of CTLs and NK cells." (PMID 36479129, 2022). "The data thus collectively indicated that TLR4-mediated Bcl6 induction was essential for macrophages differentiation underpinning tumor progression." (PMID 36542153, 2022). "The expression of HMGB1 and TLR4 was significantly high in tumor tissue compared with that in normal tissue, the expression of CCL28, KLF2 and TNFSF18 in tumor were similar to normal tissues." (PMID 36204682, 2022). "Next, we use sparstolonin B to activate the TLR4 signal for confirming the tumor-regulated effect of the ASCL2, following which we observe the changes." (PMID 36008864, 2022). "It has been revealed that DAMP-derived molecules in the tumor microenvironment induce chronic inflammation via TLR-4." (PMID 36142391, 2022). "In CRC, elevated TLR4 expression is observed in all tumor components, such as the epithelial, endothelial, and stromal layers, while TLR4 is expressed at a very low level in normal colorectal cells." (PMID 35327577, 2022). "Tumor-derived exosomal Has-circ-0048117 inhibits miR-140 expression, upregulates the TLR4 expression, and promotes M2 polarization." (PMID 36071472, 2022). "The activation of TLR4 enhances tumor growth or metastasis and protects cancer cells from apoptosis or immune cell-induced lysis." (PMID 35955552, 2022). "Inhibitors of PI3Kγ or mTOR as well as agonists of CD40, TLR4, -7, -8, or -9 can repolarize macrophages towards a proinflammatory phenotype promoting tumor suppression in preclinical studies." (PMID 36237314, 2022). "In the study, we reveal that tumor-derived signal, redHMGB1 specifically, is sensed by TLR4 on TAMs and acts through mTORC1-mediated translational machinery to control Bcl6 expression." (PMID 36542153, 2022). "NETs were also shown to enhance cancer metastasis by activating tumor-intrinsic TLR4/9-cyclooxygenase 2 (COX2) inflammatory pathways." (PMID 35574410, 2022). "On the contrary, TLR4 activation also leads to the production of IFNβ by tumor cells, contributing to an anti-tumor immune response." (PMID 36224342, 2022). "Actinomyces induces activation of the TLR2/NF-κB and TLR4/NF-κB pathways to promote inflammation and suppress anti-tumor responses by inhibiting the infiltration of CD8+ T lymphocytes." (PMID 36119074, 2022). "Gut microbiota-stimulated cathepsin K secretion mediates TLR4-dependent M2 macrophage polarization and promotes tumor metastasis in colorectal cancer." (PMID 35110624, 2022). "The result showed that removal of TLR4+/+ macrophages significantly reduced tumor sizes, whereas depletion of TLR4−/− macrophages increased tumor mass." (PMID 36542153, 2022). "Tumour cells release high-mobility group box 1, which binds to toll-like receptor 4 (TLR4) on platelets and leads to their activation." (PMID 36558983, 2022). "Lipopolysaccharide (LPS) is a specific ligand of Toll‐like receptor 4 (TLR4) and is known to regress tumors by regulating the cytokine generation and recruitment of immune cells at the tumor site." (PMID 34689394, 2022). "TLR4 activation enhances the immunosuppressive properties of tumor cell-derived exosomes, allowing tumor cells to evade immune surveillance or promote the development of tumor metastasis." (PMID 36365103, 2022). "At 72 h, colon and tumour tissue were collected and examined for histopathological changes and RT-PCR for genes of interest; TLR4, MD-2, CD-14, MyD88, IL-6, IL-6R, CXCL2, CXCR1, and CXCR2." (PMID 35962138, 2022).
tumor (continued). "Mechanistically, the microbiome has been reported to affect tumor-specific CD8+ T cells via TLR4 or TLR9/MyD88 signaling and the IL-12 pathway." (PMID 36387171, 2022). "Collectively, this evidence suggests that supplementation with BRB in mice consuming a standard diet decreased inflammatory cytokines, ameliorated TLR4 dysregulation and reduced methylation of tumor suppression genes." (PMID 36558431, 2022). "Tumor-cell-derived exosomes transport high-mobility group box-1 (HMGB1) to interact with Toll-like receptor 4 (TLR4) and activate the neutrophil nuclear factor kappa-B (NF-κB) pathway." (PMID 36230676, 2022). "In this work, we demonstrate that some components from the T. cruzi lysate have anti-tumour properties and can trigger mouse and human TLR4 and human TLR2." (PMID 36499361, 2022). "For example, TLR4 activation releases immunosuppressive exosomes, promotes tumor progression, and accelerates the metastatic process." (PMID 36401285, 2022). "Through activation of MC via TLR4, MC secrete CXCl10, which recruits tumor-specific T cells for effective antitumor responses." (PMID 35326379, 2022). "Upon binding to TLR-4, signaling cascades are initiated that regulate inflammation and NF-κB-dependent tumor development." (PMID 35697899, 2022). "Radiation induces HMGB1 release in tumor microenvironment, triggering NETosis through TLR4; NETs enhance resistance to radiotherapy by suppressing CD8+ T cell infiltration." (PMID 35574410, 2022). "Their study found that intestinal sterilization and downregulation of TLR4 can reduce the incidence of liver tumors and inhibit tumor growth." (PMID 35965618, 2022). "In breast cancer, a stimulation expressed-TLR4 tumor with LPS promoted cancer cell proliferation via upregulation of IL-8 and IL-6 production." (PMID 35309296, 2022). "While TLR4 activation can increase tumour growth and immunosuppression, it can also promote anti-tumour activity." (PMID 35962138, 2022). "The data from TCGA and GTEx databases showed that the expression of TLR4 was higher in normal lung tissue than in tumor tissue." (PMID 36517836, 2022). "TLR4 and pSTAT3 represent major regulators of cancer inflammation and anti-tumor immune response; however, their role in the periphery is largely unexplored." (PMID 35205801, 2022). "At the same time, FGFR1 and TLR4 regulate tumor cell hyperplasia and migration and promote proinflammatory response production via the PI3K/Akt signaling pathway." (PMID 35342418, 2022). "HMGB1 secreted by dying tumor cells triggers the activation of IFN-γ polarizing tumor-antigen specific T-cells through a TLR4- and MyD88-dependent mechanism." (PMID 35493517, 2022). "Intestinal epithelial Caco-2 cells expressing TLR4-Asp299Gly underwent EMT and morphologic changes associated with tumor progression, whereas cells that expressed wildtype TLR4 did not." (PMID 36231099, 2022). "After 24 h, the mice were sacrificed to evaluate the expression levels of the TLR4/NF-κB/HIF-1α in tumor tissues." (PMID 35464826, 2022). "We investigated the normalized gene expression of μ, κ, δ opioid receptors (MOR, KOR, DOR), Opioid Growth Factor (OGFR), and Toll-Like 4 (TLR4) receptors in normal and tumor samples from twelve solid tumor types." (PMID 35359418, 2022). "Paclitaxel is an antineoplastic drug used to treat OV and can reduce tumor growth by polarizing M2 into M1 macrophages in a TLR4-dependent manner." (PMID 35137909, 2022). "In different solid tumor types, TLR4 is used as a biomarker to reveal tumor proliferation, differentiation, metastasis, prognosis and patient survival status." (PMID 36555339, 2022). "The TLR4 signaling pathway is also activated in a variety of tumor cells to regulate the tumor development." (PMID 35859766, 2022). "This protein was secreted by dying tumor cells after radio- and chemotherapy and interacts with Toll-like receptor 4 (TLR4) and its adaptor MyD88 expressed by DCs." (PMID 35626062, 2022).
tumor (continued). "Indirectly, tumor-derived exosomes can also polarize neutrophils into a N2 phenotype via HMGB1/TLR4/NF-κB signaling." (PMID 35163180, 2022). "These TLR4 agonists have been mostly used in combination with tumor vaccines, including DNA-, peptide- and DC-based vaccines; they have also been used in combinationwith radiotherapy and different kinds of immune-stimulating agents." (PMID 36479129, 2022). "One possible reason is that the induction of interferon gamma secretion by activation of toll-like receptor 4 occurs through the same pathway as the upregulation of CD155 expression during the activation process of T cells in the tumor immune microenvironment." (PMID 35326727, 2022). "In DCs, tumor-derived exosomal miR-203 reduces TLR4 expression and inhibits the release of downstream cytokines (e.g., TNF-α, crucial to DCs maturation, and IL-12, required for Th1 differentiation), thus promoting cancer immunosuppressive microenvironment." (PMID 35663957, 2022). "Crosstalk between myeloma cells and MSCs mediated by toll-like receptor 4 (TRL4) signaling promote tumor microenvironment transformation and drives MSCs into a phenotype promoting tumor growth and immune escape." (PMID 35886976, 2022). "Next, to explore the post-transcriptional regulation of TLR4 expression, the LIN28/let7 axis, which is involved in tumor development and is associated with inflammation, is a potential molecular target." (PMID 35955552, 2022). "Previous studies indicated that tumor cells inhibited the body’s immune defenses by expressing TLR4 and activating downstream signaling molecules to construct a local tumor microenvironment." (PMID 36267958, 2022). "Previous experiments have also shown that TLR4 expression by tumour cells can be a contributing factor that promotes tumour cell proliferation, survival, migration, and metastasis." (PMID 35962138, 2022). "HMGB1 not only binds to platelets through TLR4 but also activates TLR9-dependent pathways in tumor cells to produce the intermediate NETs." (PMID 36613779, 2022). "In contrast, TLR4, NOS2, IL-6, MIP-3α, and VEGF were highly expressed in the transplanted tumour tissues from the LPS groups, and their expression levels were decreased in the TLR4-silenced groups." (PMID 36010574, 2022). "It has been reported that TLR4 can mediate the immune escape of tumor cells and promote tumor cell to resist drug-induced apoptosis." (PMID 35898889, 2022). "In particular, TLR4 promotes tumor cell proliferation, invasion, survival and migration, the induction of epithelial–mesenchymal transition (EMT), the expansion of cancer stem-cells (CSCs), resistance to paclitaxel, and immune suppression in the TME." (PMID 35205801, 2022). "Increased attention has focused on the role of TLR4 and LPS in tumor development, and endotoxin as an important mediator of the interaction between the liver and intestinal axis." (PMID 36267958, 2022). "The vastly varied TLR4 expression was expected as TLR4 plays multiple roles in shaping the tumor microenvironment, and the latter is famously known of its complexity." (PMID 36232715, 2022). "TLR4 is widely expressed in tumor cells as well as the cells of the tumor microenvironment such as tumor-associated macrophages (TAMs), cytotoxic T cells, myeloid-derived suppressor cells, and natural killer cells." (PMID 36678520, 2022). "An increase in TLR4 immunoexpression was observed from normal oral mucosa to the epithelium surrounding OSCC to the tumor cells in OSCC." (PMID 35327577, 2022). "The siRNA that was incorporated into the micelleplex aimed to silence the expression of toll-like 4 receptors (TLR-4), which are responsible for the proliferation of tumor cells and the inhibition of apoptosis." (PMID 36015325, 2022).
tumor (continued). "The binding of extracellular high mobility box 1 (HMGB-1) to toll-like receptor 4 (TLR4) convert the immature dendritic cells, D0, into the activated tumor-associated dendritic cells at a rate proportional to HMGB-1/(H0+HMGB-1), where H0 is constant." (PMID 35015785, 2022). "Apart from their expression on various immune cells, TLRs (including TLR4) are known to be expressed on various tumor cell lines and primary tumors from various sites within the body." (PMID 35874727, 2022). "Together, our data suggested that HNRNPA2B1 promotes tumor progression of MM through the regulation of TLR4 expression." (PMID 36401285, 2022). "This is supported by other work showing conflicting roles of TLR4 in tumour response to cancer treatment." (PMID 35962138, 2022). "Corylin increased the levels of the colon tight junction markers ZO-1, claudin, and occludin in CAC mice by repairing TLR4 signaling and decreasing the phosphorylation of p38 and downregulation of inflammasome genes, thus affecting tumor progression." (PMID 35269806, 2022). "We observed no significant changes in total macrophage frequencies with ferrichrome treatment in WT or TLR4−/− mice both in the spleen and in the tumor." (PMID 36333531, 2022). "Paradoxically, the secretion of alarmin proteins (such as extracellular histones or HMGB1) by dying tumor cells has been previously shown to activate tumor antigen-specific T-cell immunity, via their action on TLR4 expressed by dendritic cells." (PMID 35562918, 2022). "High-mobility group box 1 (HMGB1), released by dying tumor cells, on the other hand, interacts with TLR4 on platelets and mediates platelet–tumor cell interaction, promoting metastasis." (PMID 35409226, 2022). "The tumor volume was monitored every week and was found to be significantly smaller in the KGM+5-FU group, while TLR4 overexpression reversed the decrease in tumor volume induced by KGM and 5-FU cotreatment." (PMID 37304412, 2022). "It is derived from the regulation of other mechanisms (such as the TLR4/MyD88 pathway) to promote tumor bone and distal metastasis." (PMID 34799997, 2022). "Cathepsin K mediates M2 macrophage polarization through a TLR4-dependent pathway and supports tumor metastasis in CRC." (PMID 35892821, 2022). "We found that Eritoran, a TLR4 inhibitor, inhibits tumor growth by immunomodulation and vascular normalization." (PMID 35780158, 2022). "The resulting data indicated that TLR4, MyD88, NF‐κB p65, and Bcl‐2 protein levels were markedly increased and Bax levels reduced after P. copri treatment compared with the tumour control group." (PMID 35735103, 2022). "Presence of TLR4-immunoreactivity was spotted in both cytoplasm and surface of OC tumor cells in paraffin-embedded OC patient tissue sections, and the same expressional pattern for TLR4 was also founded in A2780, CP70, R182, and R179 OC cell lines." (PMID 36588690, 2022). "Tumors with higher NK and T cell infiltration exhibited significantly increased expression of the pro-inflammatory receptor TLR4 in sorted CD45- tumor cells." (PMID 35874727, 2022). "It was observed that RA also lowered the anti-apoptotic factors that promoted tumour development and suppressed toll-like receptor 4 (TLR-4) in the inflammatory condition." (PMID 36365218, 2022). "Increased cholesterol outflow increased lipid content in the TME to provide nutrition for tumor cell growth and destroyed the lipid raft of TAMs to weaken the Toll-like Receptor 4 (TLR4) signaling pathway." (PMID 36685571, 2022). "Significant increases in IFNG, IL‐18, IL‐1β, IL‐8, TNF‐α, TLR4, MyD88, and NF‐κB levels were found in the P. copri and tumour control groups." (PMID 35735103, 2022). "TLR4 is a pattern recognition receptors involved in chronic inflammation, oxidative stress and the formation of tumor microenvironment." (PMID 35531876, 2022).